CASP8 (caspase 8)
Diseases named in the same sentence as CASP8 in open-access papers (continued):
Sharing a sentence is not in itself a finding about the gene and the disease.
breast carcinoma (continued). "Methylation specific PCR (MSP) and bisulfite sequencing were used for determination of proapoptotic gene Caspase 8 (CASP8) and the tumor suppressor gene maspin promoter methylation in four breast cancer and two non-tumorigenic breast cell lines." (PMID 20132554, 2010). "CASP8 mRNA level were decreased significantly in all four breast cancer cells compared to non-tumorigenic breast cells, MCF-10." (PMID 20132554, 2010). "The CpG sites in the promoter region of CASP8 and maspin were methylated in all four breast cancer cell lines but not in two non-tumorigenic breast cell lines." (PMID 20132554, 2010). "Results from MSP showed that CASP8 promoter was methylated in breast cancer cells, MCF-7, MB231, SKBR3, and HCC1937; but not in non-tumorigenic breast cells, MCF-10." (PMID 20132554, 2010). "We further show that the same assay can be applied to breast cancer cells expressing a silencing caspase-8 shRNA or a non-silencing scrambled control." (PMID 20967281, 2010). "The CASP8 promoter methylation resulted in the gene silence and lack of CASP8 in those breast cancer cells." (PMID 20132554, 2010). "The predictions revealed that the mechanism of sinapic acid in breast cancer may be due to multiple pathways and proteins like β-catenin, PRKCA, CASP8, and cytochrome enzymes (CYP1A1 and CYP3A4); the majorly regulated pathway was predicted to be “Pathways in cancer”." (PMID 38081857, 2023). "The predictions revealed that the mechanism of sinapic acid in breast cancer may be due to regulation of multiple proteins like CTNNB1, PRKCA, CASP8, SIRT1, and cytochrome enzymes (CYP1A1 & CYP3A4); the majorly regulated pathway was predicted to be ‘Pathways in cancer’." (PMID 38081857, 2023). "In the breast carcinoma cell line MDA-MB-231, however, the agonistic antibodies C#16 and C#22 were, alone, less efficient, owing to the fact that this cell line is naturally resistant to TRAIL-induced apoptosis due to high expression levels of the caspase-8 inhibitor cFLIP34." (PMID 30718507, 2019). "Despite the activation of initiator caspase 8 and 9, in our experimental conditions the canonical apoptosis pathway was not reaching the end, as both DNA ladder and PARP-1 proteolysis were absent; the absence of PARP-1 proteolysis was recently described also in HMA-treated breast cancer cells." (PMID 27816051, 2016). "Similarly, we suggest that caspase-8 does not play any significant role in cell death induction by taxanes in breast cancer cells." (PMID 25685064, 2015). "In breast cancer cell line MCF-7 and HeLa cells, PEA-15 overexpression inhibits Fas ligand (FasL) and Fas/TNFα apoptotic effects by blocking the interaction between FADD and caspase-8, preventing the recruitment and activation of caspase-8 at the death-inducing signaling complex (DISC)." (PMID 26263999, 2015). "Therefore, caspase-8/GSDMC initiated a non-canonical pyroptosis pathway in breast cancer cells." (PMID 33634141, 2021). "However, DRβ-H did not affect caspase-8 in breast cancer cells (Data not shown)." (PMID 24603880, 2014). "All four breast cancer cell lines, MCF-7, MB231, SKBR3 and HCC1937, lacked protein expression of caspase-8." (PMID 20132554, 2010). "The methylation status of CASP8 can be completely or partially reversed by treatment with 5-aza-dc in MB231, SKBR3, and BT474, but not in MCF-7 breast cancer cells." (PMID 20132554, 2010). "As for T47D cells, significant cleavage of caspase-3 but not caspase-8 and PARP was found at dosage as low as 10μM following 48 hours treatment, suggesting simvastatin-induced apoptosis was more caspase-3 dependent in a subpopulation of breast cancer cells." (PMID 26565813, 2016). "Overexpression of Bcl-2 and Bcl-xL resulted in the reduction of TRAIL-induced cleavage of caspase-8 and Bid, cleaved blockage of caspase-3, -7, and -9 in non-small-cell lung cancer (NSCLC) and the cleavage of caspase substrates like PARP in glioblastoma, neuroblastoma, and breast cancer cell lines." (PMID 37065863, 2023).
colon carcinoma (107 papers, 2002 to 2025). "The elevation of Fas protein expression and raising active forms of caspase 8 and caspase 3 had been associated with bovine lactoferrin-induced apoptosis in the colon carcinoma model." (PMID 37422619, 2023). "Previous studies have indicated that polymorphisms in CASP3 and CASP8 are related to colon cancer, and the VEGFA was also significantly associated with rectal cancer." (PMID 33101392, 2020). "In this context, recent pilot investigations reported a negative prognostic impact for the CASP8 -652 Del allele or the CASP8 302His allele for patients with colon cancer or neuroblastoma, respectively." (PMID 27507139, 2016). "Caspase-8 has been reported to be mutated in colon cancer, and these mutations interfere with apoptosis." (PMID 25980443, 2015). "These mutants were different from the colon cancer-derived ones, and most of them encoded caspase-8 molecules defective in apoptosis induction." (PMID 24281211, 2010). "In contrast, catalytically active caspase-8 has been implicated in the acquirement of invasive properties in TRAIL-stimulated colon cancer cells expressing a mutant form of PI3 kinase." (PMID 24281211, 2010). "Numerous studies have reported that the loss of caspase-8 expression occurs in medulloblastoma, colon carcinoma, more frequently in small cell lung carcinoma, glioma and malignant neuroblastoma." (PMID 19331667, 2009). "Similar to the mitochondrial dysfunction and caspase-3/7 activation exhibited in A375 and HT-29 cells by our study, isoledene-rich plant fractions have been demonstrated to cause ROS generation, ΔΨm loss, cytochrome c release, and caspase-8/9/3 activation in HCT116 colon cancer cells." (PMID 41515343, 2025). "It was proposed that the presence of mutant caspase-8 in colon carcinomas showed that mutations in the CASP8 gene may have resulted in the loss of its apoptotic function and restoration of this activity may promote tumor apoptosis for the treatment of CRC." (PMID 34836311, 2021). "The investigation also explored the effect of caspase-4 activation and the activation sequences of caspase-2, caspase-8, and caspase-3 on the apoptosis of human colon cancer LoVo and SW480 cells." (PMID 41011202, 2025). "In summary, SS-a induces apoptosis by facilitating the sequential activation of caspase-4, caspase-2, caspase-8, and caspase-3, thereby inhibiting the proliferation of colon cancer cells." (PMID 41011202, 2025). "According to the results treating colon cancer cells with the nanoparticles significantly increased the expression of the CASP8 gene by 3.8 folds." (PMID 38360831, 2024). "Our study showed that Ag@Gln-TSC NPs significantly up-regulated the expression of the CASP8 gene in the colon cancer cell line." (PMID 38360831, 2024). "In one study, parental DLD1 human colon cancer cells developed TRAIL resistance after siRNA-mediated suppression of caspase-8 expression." (PMID 37065863, 2023). "The Src-dependent phosphorylation of Caspase-8 on Tyr380 has been shown to inhibit Caspase-8-dependent apoptosis in colon cancer cells and promote cell migration in neuroblastoma cell lines." (PMID 37444381, 2023). "Several studies have indicated that in colon cancer cells, the inhibition of caspase-8 activity in the extrinsic pathway leads to heightened resistance to anoikis." (PMID 37667281, 2023). "Collectively, these results reveal that cFLIPL levels play a key role to control TRAIL-R2-mediated caspase-8 activation and apoptosis in colon cancer cells undergoing ER stress." (PMID 35115486, 2022). "Colon cancer cells treated with 7HF have also shown concurrent upregulation of caspase-8, 9 and 3 expression (in intrinsic and extrinsic pathways)." (PMID 35056723, 2022).
colon carcinoma (continued). "We have investigated in both two-dimensional (2D) cultures and multicellular tumor spheroids (MCTSs) the role of caspase-8 inhibitor cFLIP as a regulator of the balance between apoptosis and survival in colon cancer cells undergoing ER stress." (PMID 35115486, 2022). "A further study revealed that the expression of procaspase-8 and−3 was downregulated and the activity of caspase-8,−3,−6, and−7 was increased in human colon cancer LoVo cells through the TRAIL/DR pathway after treatment with laminarin." (PMID 36059851, 2022). "Some studies address the role of SPARC in activating caspase-3 and caspase-8 dependent apoptosis, which reveals a potential benefit of physical exercise in decreasing the incidence of colon cancer." (PMID 33807959, 2021). "In a study, decreased expression of Fas, Fas ligand (FasL), and pro-caspase-8 were determined in colon cancer cells upon 5-FU treatment, suggesting the promotion of resistance through the extrinsic pathway." (PMID 34571731, 2021). "3-O-acetyloleanolic acid induced the increase of caspase-8 and caspase-3 levels in human colon carcinoma HCT-116 cells." (PMID 32998255, 2020). "In the same line, present work provides scientific evidence that EGCG sensitizes colon cancer cells to TRAIL induced apoptosis via caspase 8 and DR5 signaling." (PMID 32283836, 2020). "TIPE2 was up-regulated in the cytoplasm of colon cancer tissues and HT-20 colon cancer cells by inhibiting caspase-8 activity." (PMID 33817189, 2019). "In thyroid, ovarian, and colon cancer cells, evodiamine led to the activation of caspase-3, caspase-8, and caspase-9." (PMID 29690562, 2018). "Former studies illustrated that kaempferol increased the levels of membrane-bound FAS ligand, decreased uncleaved caspase-8 and intact Bid, and increased caspase-8 activity in HT-29 human colon cancer cells." (PMID 29734760, 2018). "Saikosaponin a (SSa), a bioactive phytochemical from Bupleurum, triggers sequential caspase-2 and caspase-8 activation, and thereby induces caspase-mediated apoptosis in human colon carcinoma (HCC) cells." (PMID 29245990, 2017). "In this study, we report that NHLRC2 is cleaved by caspase-8 in ROS-induced apoptosis in the HCT116 human colon cancer cell line." (PMID 29242562, 2017). "Here we show that the NHL-repeat-containing protein 2 (NHLRC2) thioredoxin-like domain protein is cleaved by caspase-8 in ROS-induced apoptosis in the HCT116 human colon cancer cell line." (PMID 29242562, 2017). "The simultaneous activation of MAPK, NF-κB, and caspase 8 and their respective functions in colon carcinoma cells remains to be determined." (PMID 27487939, 2016). "As mitochondrial membrane destabilization was observed in colon cancer cells treated with DRE, we wanted to confirm the link between caspase-8 activation and the loss of mitochondrial membrane potential." (PMID 27564258, 2016). "Clearly, the components of the DRE extract can stimulate/inhibit other signaling pathways in colon cancer cells and induce apoptosis, bypassing the requirement for caspase-8." (PMID 27564258, 2016). "Since the DRE triggered cell death of colon cancer cells appeared to be caspase-8 independent, we proceeded to examine its effects on the expression cell death related genes in order to uncover other aspects of the DRE action." (PMID 27564258, 2016). "In the case of colon cancer cell apoptosis, tBid expression was also enhanced, indicating a contribution of caspase-8 also to the activation of the mitochondrial pathway." (PMID 26821053, 2016).
colon carcinoma (continued). "We also observed that BV induced the increasing expression of DR downstream apoptotic proteins such as cleaved caspase-3, cleaved caspase-8, cleaved caspase-9 and Bax but decreased expression of Bcl-2 in colon cancer cells." (PMID 26561202, 2015). "Note that activation of caspase-2 has been reported to activate caspase-8, and sequential activation of caspase-2 and -8 is essential for saikosaponin a-induced apoptosis in human colon cancer cells." (PMID 25227113, 2014). "In order to confirm this pathway, caspase-9, caspase-3 and caspase-8 activation were observed in LoVo colon cancer cells." (PMID 25342273, 2014). "TRAIL-induced activation of caspase-8 can be enhanced by doxorubicin (Dox) in the colon cancer cell line HT29." (PMID 24147007, 2013). "Induction of TRAIL-R1 and TRAIL-R2 expression and caspase-8, -10, -9, -3 activation in SW-480 colon cancer cells by kaempferol are sufficient to restore TRAIL sensitivity." (PMID 24324518, 2013). "Paclitaxel was also reported to induce apoptosis involving caspase 8 activation in colon cancer cell (HT-29-D4)." (PMID 23737847, 2013). "We demonstrated that Res inhibited human colon cancer cell growth and found that Res induced Caspase-8/Caspase-3-dependent apoptosis through autophagy via ROS production." (PMID 22218562, 2012). "Taken together, our data suggest that IFN-γ and TNFα sensitize human colon carcinoma cells to TRAIL-induced apoptosis also through modulating caspase 8 activation." (PMID 21264227, 2011). "IFN-γ is known to increase caspase 8 expression and, consequently, to sensitize cancer cells (including colon cancer cells) to rhTRAIL." (PMID 21272366, 2011). "It has also been reported that pretreatment of HT-29 and HCT116 colon cancer cells with individual caspase-8 or caspase-9 inhibitors (Z-IETD-FMK and Z-LEHD-FMK, respectively) prior to fucoidan exposure reduced the levels of caspases, including caspase-3." (PMID 22363242, 2011). "Following 40 hours treatment with the novel antagonist peptide, colon cancer cell Caspase 3/7 activities increased 2–7 times; Caspase 8 activities increased 2–5 times and Caspase 9 increased 1.2–1.6 times." (PMID 18261206, 2008). "Although in other model systems like colon cancer or liver cancer induction of Caspase 3 by 4-PB treatment was described, we found only Caspase 8 to be upregulated." (PMID 17164759, 2007). "A 2014 study was conducted to better understand the mechanism of TIPE2 via caspase 8 in colon cancer patients, and the study discovered that TIPE2 was dominantly expressed in colon cancer tissues and its expression was linked to lymph node distant metastasis and the Dukes stage of CRC." (PMID 40558596, 2025). "Furthermore, SS-a was found to activate the expression of apoptosis-inducing proteins, including caspase-4, caspase-2, caspase-8, and caspase-3, in colon cancer cells." (PMID 41011202, 2025). "The present study demonstrated that CMOSs could inhibit tumor growth but induce cell cycle arrest and apoptosis by activating caspase-8, –9, and –3/7, and ROS generation through both intrinsic and extrinsic mechanisms in human colon cancer cell line HCT116." (PMID 38259721, 2024). "MM131 led to the activation of caspase-8 in colon cancer cell lines." (PMID 33918514, 2021). "MM137 was the most effective activator of caspase-8 in colon cancer cells." (PMID 32717981, 2020). "Taken together, these results suggest that excess ROS production causes a caspase-8-mediated decrease in NHLRC2 protein levels, leading to apoptotic cell death in colon cancer cells, indicating an important role for NHLRC2 in the regulation of ROS-induced apoptosis." (PMID 29242562, 2017). "We then aimed at testing the hypothesis that these ceramide analogs modulate caspase 8 activation to increase human colon carcinoma cell sensitivity to FasL-induced apoptosis." (PMID 27487939, 2016).
colon carcinoma (continued). "However, combination of a ceramide analog with FasL increased procaspase 8 degradation and generation of active caspase 8 in all three human colon carcinoma cell lines tested." (PMID 27487939, 2016). "Furthermore, we demonstrated that extrinsic apoptosis pathway was involved in apoptosis-promoting effect of TSLP, as cleaved caspase-8 was greatly increased in TSLP-treated colon cancer cells and caspase-8 inhibitor markedly decreased cancer cell apoptosis." (PMID 26919238, 2016). "Therefore, DRE treatment efficiently activated the extrinsic pathway of apoptosis in colon cancer cells and the results confirm the localization of caspase-8 before and after activation." (PMID 27564258, 2016). "More intriguingly, tyrosine phosphorylation of caspase-8 has also been shown in colon cancer cells, suggesting that post-translational modification of caspase-8 protein may play a role in the pathogenesis of cancer development and progression." (PMID 27101103, 2016). "Moreover, colon cancer cells treated by the two compounds were analysed for caspase 3 and caspase 8 activities by fluorogenic substrate cleavage." (PMID 24874286, 2014). "Furthermore, inhibition of the PI3K/Akt pathway increases the cleavage of caspase 8 in colon cancer cells treated with E-selectin and this effect is still further increased when both ERK and PI3K pathways are concomitantly inhibited." (PMID 21722370, 2011). "Indeed, reduced levels of Fas and pro-caspase-8 were observed in 5-FU-resistant colon cancer cells." (PMID 34571731, 2021). "In RKO and HT-29 colon cancer cells, AdoMet treatment reduced the expression of several anti-apoptotic genes such as the gene encoding FLICE-like inhibitory protein and caused the activation of caspase 8 with the consequent release of cytochrome from the mitochondria." (PMID 33374288, 2020). "Therefore, therapeutic means to enhance Fas oligomerization to increase caspase 8 activation may represent an effective approach to increase colon carcinoma cell sensitivity to FasL-induced apoptosis to suppress colon carcinoma cell immune evasion." (PMID 27487939, 2016). "Moreover, RES induced autophagy in human U251 glioma cells, decreased the intracellular reactive oxygen species level, which correlated with the induction of caspase-8 and caspase-3 cleavage in human colon cancer cells and induced apoptosis in patients with chronic myeloid leukemia cells." (PMID 24672638, 2014). "In colon cancer, caspase-8 mutants were exclusively detected in carcinomas (5.1%), and three of the five mutants were shown to interfere with apoptosis induced by death receptor overexpression suggesting they might behave in a dominant-negative manner in the tumor cells." (PMID 24281211, 2010). "In this present study, we demonstrated that nutlin-3a inhibits colon cancer in vivo and in vitro by triggering CHOP/DR5/caspase-8-dependent apoptosis." (PMID 40264676, 2025). "Excess reactive oxygen species (ROS) production led to a caspase-8-mediated decrease in NHLRC2 protein levels, leading to apoptotic cell death in colon cancer cells, suggesting an important role for NHLRC2 in the regulation of ROS-induced apoptosis." (PMID 37179546, 2023). "In the colon cancer cell line LS174T, the HDAC inhibitors (HDACis) TMP269 and SAHA decreased HDAC7 levels, leading to upregulation of p21, ATF3, and caspase 8 (CASP8) expression and downregulation of BCL2 expression." (PMID 37631010, 2023).